CFTR (CF transmembrane conductance regulator)
Diseases named in the same sentence as CFTR in open-access papers (continued):
Sharing a sentence is not in itself a finding about the gene and the disease.
cystic fibrosis (continued). "Cystic fibrosis is an incurable, chronic disease, caused by defects in genes encoding for the CF transmembrane conductance regulator (CFTR), a chloride channel which regulates the activity of other chloride and sodium channels at the cell surface epithelium." (PMID 33048281, 2021). "Cystic fibrosis is an autosomal-recessive multiorgan disease caused by mutations in the cystic fibrosis transmembrane conductance regulator (CFTR) gene on chromosome 7." (PMID 34070354, 2021). "This investigation aims to detect the types and frequencies of certain CFTR mutations among a group of clinically diagnosed Iraqi cystic fibrosis children." (PMID 38624701, 2021). "Cystic fibrosis is an inherited autosomal recessive disease that is caused by mutations in the cystic fibrosis transmembrane conductance regulator (CFTR) gene." (PMID 33643573, 2021). "Deletion of phenylalanine at position 508 (F508del) in the CFTR chloride channel is the most frequent mutation in cystic fibrosis patients." (PMID 34067708, 2021). "Cystic fibrosis is a genetic autosomal recessive disease, due to mutations in the CFTR (cystic fibrosis transmembrane conductance regulator) gene, with the most frequent one being CFTRdel506." (PMID 34459017, 2021). "Cystic fibrosis is caused by mutations in the cystic fibrosis transmembrane conductance regulator (CFTR), which lead to early death due to progressive lung disease." (PMID 34615919, 2021). "Cystic fibrosis is a genetic disease caused by mutation in the gene encoding the Cystic Fibrosis Transmembrane Conductance Regulator (CFTR)." (PMID 34571712, 2021). "Cystic fibrosis is a progressive genetic disease caused by mutations in the cystic fibrosis transmembrane conductance regulator (CFTR)." (PMID 35008532, 2021). "Drugs called CFTR modulators improve the physiologic defect underlying cystic fibrosis and alleviate many disease manifestations." (PMID 34903059, 2021). "Although the CFTR gene, which is mutated in cystic fibrosis, was cloned in 1989, significant progress in the development and approval of CFTR-targeting therapeutics has only occurred in the last decade." (PMID 34947992, 2021). "In cystic fibrosis, p.Phe508del is the most frequent mutation in the Cystic Fibrosis Transmembrane conductance Regulator (CFTR) gene." (PMID 34831204, 2021). "Cystic Fibrosis is a recessive genetic disease caused by a defect in the transmembrane protein that transports chloride across the cellular membrane (CFTR)." (PMID 34073260, 2021). "Cystic fibrosis is an autosomal recessive disease caused by mutations in the cystic fibrosis transmembrane regulator (CFTR) gene: the gene product responsible for transporting chloride and bicarbonate ions through the apical membrane of most epithelial cells." (PMID 34202364, 2021). "Cystic fibrosis is an autosomal recessive multisystem disease that results from mutation(s) of the cystic fibrosis transmembrane conductance regulator (CFTR) gene." (PMID 38624701, 2021). "For example, studies on the biosynthesis of the cystic fibrosis transmembrane conductance regulator (CFTR) F508 deletion mutant (which leads to cystic fibrosis), showed that the mutation leads to misfolding and ER trapping of the mutant protein." (PMID 34830210, 2021). "Cystic fibrosis is a severe autosomal recessive disorder caused by mutations in the cystic fibrosis transmembrane conductance regulator (CFTR) gene encoding the CFTR protein, a chloride channel expressed in many epithelial cells." (PMID 34685773, 2021). "In cystic fibrosis, inactivating mutations in the cystic fibrosis transmembrane conductance regulator (CFTR) result in loss of control of the pH of the fluid layer covering the epithelium into which AMPs and their partners are secreted." (PMID 34579574, 2021). "Cystic fibrosis lung disease results from a series of functional changes due to mutations in the CF transmembrane conductance regulator (CFTR)." (PMID 34831482, 2021).
cystic fibrosis (continued). "Cystic fibrosis is a genetic disorder caused by mutations in the CFTR gene encoding Cystic Fibrosis Transmembrane Conductance Regulator (CFTR)." (PMID 34641953, 2021). "Cystic fibrosis is an autosomal recessive genetic disease caused by mutation in the gene that codes for the cystic fibrosis transmembrane conductance regulator (CFTR) protein, regulating the transport of sodium and chlorine ions through epithelial cells." (PMID 34066942, 2021). "Mutations of the CFTR gene lead to cystic fibrosis, one of the most common life-threating autosomal recessive disorders." (PMID 33232302, 2021). "Cystic fibrosis is a genetic disorder caused by mutations of a gene encoding a multifunctional protein, the cystic fibrosis transmembrane regulator (CFTR), expressed on the apical membrane of epithelial cells and submucosal glands." (PMID 33477393, 2021). "Induced Pluripotent Stem Cells (iPSCs) can be differentiated into epithelial organoids that recapitulate the relevant context for CFTR and enable testing of therapies targeting Cystic Fibrosis -causing mutant proteins." (PMID 34943927, 2021). "Cystic fibrosis is a monogenetic, autosomal, recessive disease caused by mutations in the cystic fibrosis transmembrane conductance regulator (CFTR) gene." (PMID 34604301, 2021). "Cystic fibrosis, the most common inherited disease in Caucasians, is caused by mutations in CFTR, the most frequent of which is F508del." (PMID 35004859, 2021). "Cystic fibrosis is an autosomal recessive disorder, caused by diverse genetic variants for the CF transmembrane conductance regulator (CFTR) protein." (PMID 34901273, 2021). "CFTR modulators were evaluated in clinical trials enrolling patients with cystic fibrosis bearing well-described and quite common mutations." (PMID 34685773, 2021). "Cystic Fibrosis is an autosomal recessive disorder caused by mutations in the Cystic Fibrosis Transmembrane Conductance Regulator (CFTR) gene." (PMID 33659254, 2021). "Current recommendations for CFTR analysis, in the context of spousal analysis of heterozygotes or ultrasound suspicion of Cystic Fibrosis, are to look for the most frequent mutations according to geographical origin." (PMID 33946859, 2021). "Cystic fibrosis is an inherited disorder, caused by mutations of the cystic fibrosis transmembrane conductance regulator (CFTR) gene." (PMID 33173809, 2021). "Cystic fibrosis is an autosomal recessive genetic disease caused by variants in the cystic fibrosis transmembrane conductance regulator (CFTR) gene." (PMID 34086412, 2021). "Mutations in the CFTR gene cause cystic fibrosis, the most common lethal autosomal genetic disease in the Caucasian population." (PMID 34211404, 2021). "Cystic fibrosis is a life-limiting autosomal recessive genetic disorder caused by mutations in the cystic fibrosis transmembrane conductance regulator (CFTR) gene." (PMID 33412572, 2021). "For instance, cystic fibrosis is a complex disease with more than one thousand reported mutations in the human CFTR gene." (PMID 33439550, 2021). "Cystic fibrosis is a rare genetic disease caused by pathogenic variants in the CFTR (Cystic Fibrosis Transmembrane Conductance Regulator) gene, which encodes for a chloride channel expressed ubiquitously within epithelia." (PMID 33967785, 2021). "Even more impressively, deletion of phenylalanine 508 (ΔF508) the mutation of CFTR responsible for cystic fibrosis, reduces the folding efficiency, resulting in nearly 99% of mutant CFTR being degraded before it can reach the plasma membrane." (PMID 35011665, 2021). "Mutation of CFTR is the underlying cause of cystic fibrosis, one of the most life-threatening genetic diseases in northern European populations, and CFTR modulator therapy has shown remarkable effects in recent years." (PMID 34830864, 2021).
cystic fibrosis (continued). "Our research is one of the first to show the impact of the factors such as the severity of mutation in the CFTR gene, nutritional status, lung function, and P. aeruginosa prevalence on survival rate in adult patients with cystic fibrosis." (PMID 34749804, 2021). "Cystic fibrosis is a genetic disease caused by a mutation in the cystic fibrosis transmembrane conductance regulator (CFTR)." (PMID 33664232, 2021). "Cystic fibrosis is a genetic disease caused by mutations in the CF transmembrane conductance regulator (CFTR) gene, resulting in defective ion transport in the airways." (PMID 34084147, 2021). "Cystic fibrosis is caused by loss-of-function mutations in the CF transmembrane conductance regulator (CFTR) protein, an anion channel that regulates epithelial surface fluid secretion." (PMID 34680050, 2021). "NBD1, one of two ABC domains in CFTR, also contains sites for cystic fibrosis causing mutations in regulatory phosphorylation sites." (PMID 33642783, 2021). "The clinical response to cystic fibrosis transmembrane conductance regulator (CFTR) modulators is variable within people with cystic fibrosis (pwCF) homozygous for the F508del mutation." (PMID 34945848, 2021). "Cystic fibrosis is caused by genetic mutations of the CF transmembrane conductance regulator (CFTR), leading to disrupted transport of Cl− and bicarbonate." (PMID 33923029, 2021). "Cystic fibrosis is the most common autosomal recessive disease caused by mutations in the Cystic Fibrosis Transmembrane Conductance Regulator (CFTR) gene." (PMID 34830048, 2021). "Genetic analysis revealed Phe508del (c.1521_1523delCTT) and Arg1066Cys (c.3196C > T) mutations in the CFTR gene, confirming the diagnosis of cystic fibrosis." (PMID 33853553, 2021). "Mutations in the cystic fibrosis transmembrane conductance regulator (CFTR) gene cause cystic fibrosis." (PMID 33407701, 2021). "rs121909041 causes a missense mutation in CFTR and is associated with increased response to ivacaftor for the treatment of cystic fibrosis." (PMID 34316407, 2021). "Cystic fibrosis is an autosomal recessive disease caused by mutations of the gene encoding the cystic fibrosis transmembrane conductance regulator (CFTR)." (PMID 34557648, 2021). "Cystic fibrosis is caused by absence or dysfunction of the cystic fibrosis transmembrane conductance regulator (CFTR) protein which primarily affects the pulmonary and gastrointestinal systems." (PMID 34069863, 2021). "Cystic fibrosis is an autosomal recessive disorder caused by mutations in the cystic fibrosis transmembrane conductance regulator (CFTR) gene, but the primary reason for patient morbidity and mortality is often associated with pulmonary infection." (PMID 33535659, 2021). "Cystic fibrosis is an autosomal recessive disorder caused by a mutation of the cystic fibrosis transmembrane conductance regulator (CFTR) gene." (PMID 34836301, 2021). "Cystic fibrosis is caused by genetic mutations of the CF transmembrane conductance regulator (CFTR), leading to disrupted transport of Cl− and bicarbonate and CF lung disease featuring bacterial colonization and chronic infection in conducting airways." (PMID 33923029, 2021). "In cystic fibrosis resulting of mutations in the gene encoding the cystic fibrosis transmembrane conductance regulator (CFTR) the application of Ursodeoxycholic acid (UDCA) is the mainstay of therapy." (PMID 34025430, 2021). "Cystic fibrosis is a systemic disorder of exocrine glands that is caused by mutations in the Cystic Fibrosis Transmembrane Conductance Regulator (CFTR) gene." (PMID 33708199, 2021). "Pathogenic variants in the CFTR gene are responsible for cystic fibrosis but are also risk factors of CFTR-related disorders." (PMID 34065437, 2021). "Cystic fibrosis is a multisystem disorder, caused by mutations in the CF transmembrane conductance regulator (CFTR) gene." (PMID 34362426, 2021).
cystic fibrosis (continued). "Due to the high morbidity and mortality associated with CFTR dysfunction, cystic fibrosis has historically been considered primarily as a disease of childhood." (PMID 34572234, 2021). "Very recently, a humanized model of cystic fibrosis was created by inserting the human CFTR cDNA sequence harboring a G551D mutation by KI into the rat genome, downstream of the endogenous Cftr promoter." (PMID 33959146, 2021). "Linde et.al reported that in a cohort of cystic fibrosis patients with an identical CFTR mutation p.(W1282*), patients with higher baseline mRNA levels demonstrated higher readthrough rates following gentamicin treatment." (PMID 34365092, 2021). "The main objective of the present study is to determine the frequency of the CFTR causing variants in a group of follow-up patients from a multidisciplinary center of treatment for cystic fibrosis in southern Brazil, henceforth CF center (CFC)." (PMID 34874053, 2021). "Its dysfunction causes cystic fibrosis, which results in lifetime microalbuminuria in >6% of cases, indicating that CFTR defect is associated with kidney damage." (PMID 33621200, 2021). "In patients with cystic fibrosis, CFTR mutations cause high sweat Cl− levels, which, in turn, inhibit ENaC-mediated Na+ reabsorption." (PMID 33591965, 2021). "Cystic fibrosis is an autosomal recessive disorder caused by a mutation in genes for cystic fibrosis transmembrane conductance regulator (CFTR) protein." (PMID 33833927, 2021). "Cystic fibrosis is an inherited, multi-organ disease caused by mutations in the CF transmembrane conductance regulator (CFTR) gene." (PMID 33796025, 2021). "The knockdown of BAG3 by specific siRNA not only restored autophagy in cystic fibrosis but also functionally corrected mutated CFTR by enhancing its stability and facilitating its trafficking." (PMID 32724454, 2020). "Cystic fibrosis is a lethal genetic disease that is primarily caused by misfolding of the cystic fibrosis transmembrane conductance regulator (CFTR)." (PMID 32848127, 2020). "Cystic fibrosis is caused by mutations in the gene encoding the cystic fibrosis transmembrane conductance regulator (CFTR) protein, an ATP-gated anion channel, which plays a major role in regulating both secretion and absorption in many epithelial tissues." (PMID 32640650, 2020). "Cystic fibrosis is one of the most common, lethal, autosomal recessive disease and is caused by mutations in the gene encoding the anion channel cystic fibrosis transmembrane conductance regulator (CFTR)." (PMID 32256364, 2020). "Cystic Fibrosis is an autosomal recessive disease caused by mutations in the CFTR gene involved in chloride and bicarbonate transport." (PMID 32718005, 2020). "The genetic disease cystic fibrosis results from mutation in the cystic fibrosis transmembrane conductance regulator (CFTR), an ion channel primarily responsible for regulating chloride and bicarbonate transport." (PMID 32477966, 2020). "The true symptomatic form of cystic fibrosis is the result of mutations in the CFTR gene and in 95% cases of men leads to infertility." (PMID 32722328, 2020). "Cystic Fibrosis is a genetic disease that is caused by mutations in the cystic fibrosis transmembrane conductance regulator (CFTR) gene." (PMID 32092967, 2020). "Therapy with elexacaftor-tezacaftor-ivacaftor for cystic fibrosis with CFTR mutations has provided benefit." (PMID 32516941, 2020). "Cystic fibrosis is the most common lethal autosomal recessive disorder in Caucasians and is characterized by a mutation in the cystic fibrosis transmembrane conductance regulator gene (CFTR)." (PMID 33262957, 2020). "Cystic fibrosis is an autosomal recessive illness caused by the defective cystic fibrosis transmembrane conductance regulator (CFTR) gene." (PMID 33520477, 2020).
cystic fibrosis (continued). "Cystic fibrosis is an autosomal recessive disease caused by mutations in the cystic fibrosis transmembrane conductance regulator (CFTR) gene, with pediatric onset and a median life expectancy of 36.8 years." (PMID 32784514, 2020). "In 2015, Wainwright, CE showed that lumacaftor in combination with ivacaftor provided a benefit for patients with cystic fibrosis homozygous for the Phe508del CFTR mutation." (PMID 33103563, 2020). "Cystic fibrosis is a lethal autosomal recessive disease caused by mutations in the CF transmembrane conductance regulator (CFTR) gene." (PMID 32414011, 2020). "Cystic Fibrosis is a lethal autosomal recessive disease caused by mutations in the gene encoding the cystic fibrosis transmembrane conductance regulator (CFTR)." (PMID 33552140, 2020). "Cystic fibrosis is a multisystem disorder caused by dysfunction of the cystic fibrosis transmembrane conductance regulator (CFTR) protein." (PMID 33007285, 2020). "Cystic fibrosis is an autosomal recessive disorder caused by mutation of the cystic fibrosis transmembrane conductance regulator (CFTR) gene, which encodes a sodium chloride transporter." (PMID 32652003, 2020). "Cystic fibrosis is caused by LOF mutations in the cystic fibrosis transmembrane conductance regulator (CFTR)." (PMID 32759882, 2020). "Cystic fibrosis is a life-limiting autosomal recessive disorder caused by mutations in the gene encoding CFTR." (PMID 32322187, 2020). "A few years before the PRSS1 gene mutation was identified, the cystic fibrosis transmembrane conductance regulator (CFTR) gene, a causative gene of cystic fibrosis, was also reported to be a gene associated with ARP and CP." (PMID 33375361, 2020). "This is true for eluforsen in cystic fibrosis patients homozygous for the F508del‐CFTR mutation (cystic fibrosis transmembrane conductance regulator)." (PMID 32233021, 2020). "Cystic fibrosis transmembrane conductance regulator (CFTR), a cAMP-dependent anion channel, is a crucial pathogenic gene related to cystic fibrosis." (PMID 31998800, 2020). "Cystic fibrosis is caused by mutations of the CFTR gene and consequently to the malfunction of the CFTR protein in the epithelial cells of the pancreas resulting in enzyme insufficiency and thickening of gastrointestinal secretions." (PMID 32455864, 2020). "In 2011, Ramsey BW indicated that ivacaftor (VX-770), a CFTR potentiator, was associated with improvements in lung function in subjects with cystic fibrosis." (PMID 33103563, 2020). "Mutation of CFTR leads to cystic fibrosis and causes severe damage to organs in the body, especially in the lungs and digestive system." (PMID 33123317, 2020). "Cystic Fibrosis is a genetic autosomal recessive disease caused by mutations of the CF transmembrane conductance regulator (CFTR) gene, which leads to impaired ion transport in the epithelial cells of several organs including lung, pancreas, liver and gut." (PMID 32599772, 2020). "Cystic fibrosis is a recessive genetic disease caused by a mutation in the epithelial chloride channel—cystic fibrosis transmembrane conductance regulator (CFTR)." (PMID 32630625, 2020). "Successful attempts to correct trafficking defects using molecular chaperones have been reported for CFTR mutants causing cystic fibrosis or lysosomal storage disorders." (PMID 32256370, 2020). "Mutations in the CFTR gene, which causes cystic fibrosis and CFTR-related disorders, are the first cause of congenital bilateral absence of the vas deferens (CBAVD) and, therefore, obstructive azoospermia (OA)." (PMID 32155011, 2020). "Cystic Fibrosis is an inherited disease caused by mutations in the cystic fibrosis transmembrane conductance regulator (CFTR) ion channel." (PMID 31978131, 2020). "ENaC hyperactivity is also seen in cystic fibrosis patients as a result of its dysregulation caused by mutations in the cystic fibrosis transmembrane regulator (CFTR) protein." (PMID 33013490, 2020).